SLC34A2 (solute carrier family 34 member 2)
Diseases named in the same sentence as SLC34A2 in open-access papers (continued):
Sharing a sentence is not in itself a finding about the gene and the disease.
cancer (36 papers, 2013 to 2025). A tumor composed of atypical neoplastic, often pleomorphic cells that invade other tissues. "In conclusion, we analyzed a significantly large dataset of the SLC34A2 mutational data, the SLC34A2 expression data, and the survival data of cancer patients (n = 111,283)." (PMID 34944522, 2021). "In order to assess the possible role of SLC34A2as a prognostic marker of cancer, we performed the analysis of the SLC34A2 mutational data, the SLC34A2 mRNA expression data, and the survival data of cancer patients which were publicly available online." (PMID 34944522, 2021). "We conducted a survival analysis of cancer patients, taking into account the obtained mutational data and the expression profile of SLC34A2." (PMID 34944522, 2021). "The main goal of this study is to consider SLC34A2 as a potential prognostic marker of oncological diseases using the mutational, expression, and survival data of cancer studies which are publicly available online." (PMID 34944522, 2021). "Solute carrier family 34 member 2 (SLC34A2), a pH-sensitive sodium-dependent phosphate transporter, is associated with several human cancers." (PMID 28151475, 2017). "In order to consider SLC34A2 as a potential prognostic and predictive marker of oncological diseases, we performed an analysis of the mutation and expression of SLC34A2, and assessed their effect on the life expectancy of patients from cancer studies which are publicly available online." (PMID 34944522, 2021). "One hundred and eleven functionally significant mutations were discovered, and it was found that functionally significant mutations of SLC34A2 might be involved in the reduction of the life expectancy of breast (p.D68G, p.P504L) and thymus (p.A396T) cancer patients." (PMID 34944522, 2021). "We provide the first evidence suggesting that SLC34A2 restricts innate immunity, thereby likely suppressing cancer cell immunogenicity and promoting cancer progression." (PMID 41211819, 2025). "Our findings indicate that SLC34A2 is more than just a cancer cell marker but represents a prominent therapeutic target." (PMID 41211819, 2025). "All the other regions were comprised of multiple genes, including a few known cancer genes according to COSMIC Cancer Gene Census v92: SLC34A2 on 4p15.2, RET on 10q11.21, HSP90AA1 on 14q32.31, and JAK3 on 19p13.11." (PMID 35922826, 2022). "Solute carrier family 34 member 2 (SLC34A2) is an independent prognostic indicator in several cancers." (PMID 34336552, 2021). "In the same vein, several studies exploring SLC34A2 expression in other cancers have revealed a correlation between this marker and different clinicopathological parameters." (PMID 34336552, 2021). "For the data set of OV, 67 genes were identified by univariate Cox regression to be significantly associated with the cancer and seven of them, namely COL1A1, COL3A1, RPL10, ARHGAP5, LATS1, TSHR and SLC34A2, were found in the CGC data set." (PMID 32429941, 2020). "It expands another alternative strategy to inhibit cancer progression initiated by SLC34A2 in BC, that is, to target the signaling mechanisms, by the use of c-Myc inhibitors." (PMID 28151475, 2017). "U-2 OS harbors mutations in the SLC34A2 (ENST00000382051: c.1538G>T; p.R513L) and TET2 genes (ENST00000380013: c.1394C>T; p.P465L), both of which are of functional relevance in cancers." (PMID 27658049, 2016). "In this study, a database analysis identified 17 variants located in the SLC34A2 region encoding the MX35 epitope of the large extracellular domain of the sodium-dependent phosphate transporter NaPi2b in several malignant tumors, including p.T330M substitution." (PMID 40265411, 2025). "Therefore, investigating genetic variants in the SLC34A2 gene, especially within the MX35 epitope region, in patients with malignant neoplasms is critical for identifying alterations that impact the recognition of the MX35 epitope by monoclonal antibodies." (PMID 40265411, 2025).
cancer (continued). "However, the functional analyses of SLC34A2 in tumorigenesis have yielded contradictory results in different cancer models." (PMID 26910912, 2016). "The type II sodium phosphate cotransporter 2b (NaPi2b), expressed by the solute carrier family 34 member A2 gene (SLC34A2), transports Pi into cells throughout the body and is overexpressed in cancer cells." (PMID 40643473, 2025). "Two of these genes, SLC34A2 and LIPG, are involved in cancer in humans and in hypoxic responses and ROS regulation in cancer cells." (PMID 39191281, 2024). "Interestingly, our panel included genes already described to be cancer predisposition genes (FAS, ITK, KIF1B, PGR and MET) or previously reported as playing important roles in cancer (ABI1, ARID5B, DNMT3A, HEY1, KDM5C, NCOA1, NUP98, and SLC34A2), or in DNA repair process (FANCF)." (PMID 30925779, 2019). "In this report we analyzed the localization and expression pattern of the NaPi2b protein (n = 136) as well as its gene expression (n = 73) (SLC34A2) in fresh frozen ovarian borderline and malignant tumor samples." (PMID 28464843, 2017). "On the other hand, hypomethylation of oncogenes, such as retinoblastoma binding protein 6 (RBBP6), solute carrier family 34 member 2 (SLC34A2), and lymphocyte antigen 6 complex locus K (LY6K), is frequently observed in numerous cancers, facilitating aberrant gene activation." (PMID 40663150, 2025).
infection (3 papers, 2019 to 2025). The state of being infected such as from the introduction of a foreign agent such as serum, vaccine, antigenic substance or organism. "The EZH2 promoter activity was markedly decreased after the infection with si-SLC34A2, suggesting that the activation of the EZH2 promoter is dependent on SLC34A2." (PMID 30038060, 2019). "To testify the result above and further detect the connection between SLC34A2 and EZH2, we constructed stable sublines of SW480 and HT29 by infection with lenti-si-SLC34A2 or lenti-p-SLC34A2." (PMID 30038060, 2019). "Also, the infection with lenti-si-SLC34A2 decreased the expression of cyclin D1, which is the target gene of EZH2." (PMID 30038060, 2019). "The HIF1-2 DNA binding activity was measured after infection with si-SLC34A2 or p-SLC34A2 for 48 h." (PMID 30038060, 2019). "The mutation of HIF1-2 significantly increased the activation of EZH2 promoter by si-SLC34A2 infection compared with that without any mutation, indicating that HIF1-2 binding site might be involved for SLC34A2-induced EZH2 activation." (PMID 30038060, 2019). "HSV-1 infection also triggered the expression of DUX4 and SLC34A2 in SH-SY5Y neuroblastoma cells, a neuron infection model frequently used to study HSV-1 infection." (PMID 41211819, 2025). "The protein level of EZH2 was enhanced in p-SLC34A2 group, while si-HIF-1α infection resulted in EZH2 expression significantly declined in p-SLC34A2 group." (PMID 30038060, 2019). "p-SLC34A2 infection increased the expression of HIF-1α and EZH2, indicating that SLC34A2 lies on the upstream of HIF-1α and EZH2." (PMID 30038060, 2019).
SLC34A2 also shares sentences with these, for which no sentence is quoted: hypophosphatemia (6 papers); hyperphosphatemia (4); renal carcinoma (4); hepatocellular carcinoma (3); kidney failure (3); renal cell carcinoma (3); clear cell adenocarcinoma (2); kidney disease (2); melanoma (2); osteosarcoma (2); squamous cell carcinoma (2); acute myeloid leukemia (1); adenocarcinoma (1); amyotrophic lateral sclerosis (1); benign tumors (1); bladder tumor (1); breast tumor (1); cervical cancer (1); cholestasis (1); chronic kidney disease (1); colon adenocarcinoma (1); colon cancer (1); COVID-19 (1); endometrioid carcinoma (1); Hypercalciuria (1); hypertrophic cardiomyopathy (1); Infertility (1); iron deficiency (1); large cell carcinoma (1); liver cancer (1).
A further 15 diseases each share a sentence with SLC34A2 in 1 paper.